EGFR (epidermal growth factor receptor)
Diseases named in the same sentence as EGFR in open-access papers (continued):
Sharing a sentence is not in itself a finding about the gene and the disease.
lung cancer (continued). "Continuous administration of gefitinib or erlotinib in lung cancer patients with MET amplification did not interrupt tumor progression, regardless of EGFR status." (PMID 22489192, 2012). "In lung cancer, inhibition of FASN using EGCG can be achieved without parallel stimulation of fatty acid oxidation and this effect is related mainly to EGFR signaling pathway." (PMID 22769244, 2012). "Although there has been no indication of any relationship between androgens and EGFR in NSCLCs, expression of ARs has been detected in NSCLC cell lines and biopsy samples of primary lung cancers." (PMID 15870715, 2005). "It was not possible to discriminate between lung cancer and benign lung disease owing to the lack of sensitivity–specificity relationship of HER-2 and EGFR ECD levels." (PMID 15226769, 2004). "In addition to modulating EGFR signaling, we do not preclude the effects of RAC1B on other oncogenic signaling pathways, such as Wnt signaling, in lung cancer." (PMID 40548642, 2025). "Interestingly, while FAK expression was not correlated with poor prognosis for lung cancer patients in the TCGA dataset, our patient cohort revealed that FAK serves as a marker for prognosis and response to EGFR-TKIs." (PMID 41281943, 2025). "In lung cancer cell lines with the FGF2/FGFR1 pathway, targeting this resistance mechanism with EGFR-specific TKI does not significantly increase apoptosis, indicating that FGFR inhibitors may stabilize tumor progression rather than cause tumor regression." (PMID 39544292, 2024). "Companion diagnoses, such as MSI, ERBB2 staining, EGFR, BRAF, ALK fusion, and BRCA1/2, can be done before the standard treatment, which is another reason why the CGP test is not needed, as the drivers of lung cancer, colon cancer, and melanoma are already known to a certain extent." (PMID 36251535, 2023). "According to a recent study, AXL is stimulated by osimertinib after the termination of a negative feedback loop into SPRY4 in EGFR‐mutant lung cancer cells, resulting in the expression of HER3 and EGFR to maintain cell survival and promote osimertinib tolerance." (PMID 37638338, 2023). "Further analysis of the CANCERTOOL database revealed that the expression of FKBP10 was similar between lung adenocarcinoma bearing mutant KRAS, EGFR, and KRAS/EGFR non-mutants, suggesting that the relevance of FKBP10 in lung cancer is not limited to a specific genotype." (PMID 37201304, 2023). "In lung cancer, AGR2 can modulate EGFR-TKI resistance in EGFR-mutant non-small cell carcinoma." (PMID 36327302, 2022). "The results showed that EGFR signaling could govern MEK/ERK pathway more strongly, however, the situation is not the same in BRAFV600E mutant lung cancer, which induce the receptor tyrosine kinases (RTKs) resistance problem." (PMID 36619616, 2022). "Since there is no known functional impact of RBM10 on EGFR-mutant lung cancer treatment, we tested the hypothesis that RBM10 inactivation may modulate EGFR TKI sensitivity in EGFR-mutant LA." (PMID 35579943, 2022). "However, unlike EGFR or ALK, BRAF has relatively low prevalence in lung cancer, and this study was conducted with untreated patients." (PMID 36076922, 2022). "In the large Japanese Lung Cancer Registry study of patients with lung cancer diagnosed in 2012, the 3-year survival rate was only 17% for those with NSCLC who received chemotherapy but no EGFR tyrosine kinase inhibitor, suggestive of no actionable genomic alterations as in the present study." (PMID 35740512, 2022). "generated EGFR-redirected CAR-Ts using the non-viral piggyBac transposon system, and reported that these cells demonstrated tumoricidal activity against EGFR-positive cells in vitro and suppressed tumor growth in human lung cancer xenografts." (PMID 36483567, 2022).
lung cancer (continued). "Based on preclinical studies indicating that metformin can sensitize lung cancer cells to tyrosine kinase inhibitors (TKIs), a combination of gefitinib, a TKI-targeting mutant epidermal growth factor receptor (EGFR), and metformin was tested in nondiabetic NSCLC patients." (PMID 35631452, 2022). "However, these current biomarkers, such as epidermal growth factor receptor (EGFR) and Kirsten rat sarcoma virus (KRAS) oncogene homologs, do not fully represent the complex mechanisms of lung cancer progression." (PMID 35321944, 2022). "However, the efficacy of combined EGFR and VEGF blockade was not addressed in lung cancer patients complicated with MPE, particularly in pleural endothelial cells." (PMID 34680445, 2021). "The functions of EGFR-TKIs, checkpoint inhibitors, and traditional chemotherapy have been widely studied in NSCLC patients, while the role of MEK inhibitors in the treatment of lung cancer has not been clearly described." (PMID 33402199, 2021). "For example, CD133 and CD44 aptamer-conjugated dual-targeted nanomicelles loaded with gefitinib, an epidermal growth factor receptor (EGFR) inhibitor, more effectively eradicated CD133/CD44 double-positive lung cancer-initiating cells compared with the single-targeted or non-targeted nanomicelles." (PMID 34064635, 2021). "While DHHC20 is important for EGFR palmitoylation and Kras-driven lung cancer formation, we have not ruled out the possibility that other DHHC enzymes may also palmitoylate EGFR or other RTKs." (PMID 34610265, 2021). "When the highly EGFR-expressing lung cancer cell line HCC87 and EGFR-negative human kidney 293T cells were compared for uptake of peptide-conjugated triangular gold nanoplates, there was a significantly higher internalisation in the HCC87 than in the 293T cells." (PMID 34683944, 2021). "However, despite the success in patients with lung cancer, GBM has not benefitted from the use of EGFR TKIs." (PMID 33142709, 2020). "Protein tyrosine kinase 2 (PTK2) expression has been reported in various types of human epithelial cancers including lung cancer; however, the role of PTK2 in epidermal growth factor receptor (EGFR)-mutant non-small cell lung cancer (NSCLC) has not been elucidated." (PMID 31791326, 2019). "Indeed we have observed in case reports that non-responding metastatic do not have molecular expression of the primary site (EGFR, ALK, ROS1, ALK or PD-L1) or there are cases where we have a different lung cancer or lung cancer transformation 34-36." (PMID 31598145, 2019). "Kirsten rat sarcoma (KRAS) mutations occur in about 30% of lung adenocarcinomas, and unlike other common oncogenic drivers (such as epidermal growth factor receptor (EGFR) and anaplastic lymphoma kinase (ALK)), effective targeted therapeutic strategies for KRAS mutant lung cancer have been limited." (PMID 30986992, 2019). "Interestingly, although not in lung cancer, a recent report show that APE1 was involved in EGFR activation." (PMID 30382076, 2018). "Since two patients (cases 20 and 22) did not undergo follow-up after lung cancer diagnosis, and one patient (case 21) died during EGFR-TKI treatment, tumor response to EGFR-TKI in the three additional EGFR mutant cases could not be verified." (PMID 30526536, 2018). "Interestingly, we observed that the miR‐205/ERRFI1/EGFR regulatory axis can operate also in not‐addicted cells, as ectopic miR‐205 expression in A549 lung cancer cells resulted in ERRFI1 downregulation and increased EGFR expression/activation." (PMID 30021798, 2018). "The antitumor activity of the novel EGFR inhibitor (cAMP-H3BO3 complex) with or without an oxidative phosphorylation uncoupler (thyroxine sodium) was investigated in vitro and in a nude mouse xenograft lung cancer model incorporating human A549 cells." (PMID 28915593, 2017).
lung cancer (continued). "Additionally, we suggest that MET and EGFR inhibitor-based therapy can be used to treat MET and HER2-overexpressing lung cancers, without receptor tyrosine kinase /RAS/RAF pathway alterations." (PMID 28806950, 2017). "Feedback phosphorylation of EGFR at Thr669 by ERK has been found to negatively regulate constitutive EGFR tyrosine kinase activity and HER3‐driven Akt activation by suppressing heterodimerization of EGFR/HER3 in lung cancer and triple‐negative MDA‐MB‐468 breast cancer cells." (PMID 28632938, 2017). "However, the precise role of SerpinB2 in acquired EGFR-TKI resistance, which is a major barrier in the treatment of lung cancer patients, has not been explored." (PMID 27558531, 2016). "Breast metastasis from lung cancer has been reported, but not from SCLC that is transformed from lung adenocarcinoma during maintenance treatment with epidermal growth factor receptor tyrosine kinase inhibitor (EGFR-TKI)." (PMID 27488410, 2016). "DUOX1 silencing was also found to promote EGFR TKI resistance and enhance features of CSCs, suggesting the significance of DUOX1 silencing in lung cancer as a possible indicator of lung cancers with poor prognosis or lack of responsiveness to common anticancer therapy." (PMID 27694834, 2016). "Furthermore, SALL4 knockdown also inactivated the IGF1R/EGFR downstream intermediate target AKT, as seen from downregulation of phospho-AKT, but not MAPK in the four lung cancer cell lines examined." (PMID 27705911, 2016). "However, since the expression of EGFR is much lower in A549 cells than other lung cancer cells, it is possible that PA-MSHA inhibit the activities of AKT or ERK of A549 through other pathways rather than EGFR signaling." (PMID 27283902, 2016). "In a recent study oflung cancers with wild-type EGFR, the activation of EGFR upregulated SOX2, therebydecreasing apoptosis through BCL2L1, a phenomenon that was notably absent inEGFR-mutant lung cancers.A similar pathway was reported in a prostate cancer cell line, also with wild-typeEGFR." (PMID 25686219, 2015). "Interestingly, rhodomycin A has activity in all lung cancer cell lines (A549, PC9/gef, and H1975) without particular selectivity for the EGFR status in cytotoxicity." (PMID 26312766, 2015). "To examine whether the endogenous EGFR-AURKA interactions exist in lung cancer cells and whether it is EGF dependent, we applied in situ PLA to determine the EGFR-AURKA interaction in A549 and H1975 with or without EGF stimulation." (PMID 23520446, 2013). "In the limited number of lung cancer cell lines that we studied the response to co-inhibition by PI3K inhibitors and rapamycin or to the dual inhibitor, NVP-BEZ235, was independent of wild-type or mutant EGFR status." (PMID 22355357, 2012). "EGFR, HER2, and HER3 appear to activate signalling by forming a complex with MET in a manner dependent on MET kinase activity rather than on their own kinase activity in lung cancer cells with MET amplification." (PMID 21847121, 2011). "Importantly, a large percent of lung cancer and CRC patients harboring wildtype KRAS, do not realize benefit from EGFR-targeted agents." (PMID 19439077, 2009). "However, our study broadens this knowledge by analyzing two EGFR‐mutant cell lines, unlike most RKIP studies in lung cancer, which focus on KRAS‐mutant A549 cells, thus expanding the understanding of RKIP's relevance in EGFR‐mutant settings, which account for 10–30% of NSCLC cases." (PMID 40720248, 2025). "We also examined DPP4 expression in tumor tissues from lung cancer patients by immunohistochemistry, and found that DPP4 was significantly upregulated in the residual tumor tissues after osimertinib treatment compared to the tumor tissues from patients who did not receive EGFR‐TKIs." (PMID 40479551, 2025).
lung cancer (continued). "They further assessed the relationship between TMB and specific EGFR alterations in a separate cohort of 383 EGFR mutant lung cancer cases irrespective of treatment exposure and found that EGFR 19del had a lower TMB than EGFR L858R lung tumors, which might account for the different response to ICIs." (PMID 36159795, 2022). "Cancers such as lung cancer, head and neck cancer, and melanoma have exhibited clinical benefit with IO, although patients who are never smokers (i.e., ALK, ROS, and RET) or whose tumors express mutant EGFR showed 0–14% response rates, irrespective of PD-L1 expression levels." (PMID 34001994, 2021). "The model could be a useful tool in lung cancer research targeting KRAS and EGFR negative tumors." (PMID 29415661, 2018). "Interestingly, while IFNβ strongly induced Gal-9 in human lung cancer cell lines with wildtype EGFR (A549, H441, H1229), it failed to do so in those with mutant EGFR (H1650, H1975, HCC827), suggesting that IFNβ induction of Gal-9 expression may be affected by EGFR signaling in lung cancer cells." (PMID 33547304, 2021). "Our findings reveal that a subset of EGFR-mutant, MET-amplified lung cancers develop dependence on MET activation alone, suggesting that such patients could be treated with a single-agent MET TKI rather than the current standard-of-care EGFR and MET inhibitor combination regimens." (PMID 34516823, 2021). "The results of the present study thus suggested that inhibition of the EGFR signaling pathway might not be necessary to activate the FGF2-FGFR1 autocrine loop, which may instead be induced as a response to the additional stress applied to the PC9 lung cancer cells upon pemetrexed exposure." (PMID 30838090, 2019). "In one study, using lung carcinoma cell line, EGFR inhibition did not block STAT3 phosphorylation and growth arrest, suggesting that upstream pathways, such as JAK and IL6 receptor, may play a role in activating STAT3 and contributing to oncogenesis in lung tumors, even with EGFR activation." (PMID 25763322, 2014).
non-small cell lung carcinoma (4,848 papers, 1986 to 2026). "Osimertinib is the standard first-line treatment for advanced non-small cell lung cancer (NSCLC) with sensitizing epidermal growth factor receptor (EGFR) mutations." (PMID 41694974, 2026). "We report the first case of anti-Yo antibody positive PNS in a patient with EGFR mutation-positive non-small cell lung cancer (NSCLC)." (PMID 42022512, 2026). "In cancer, EGFR amplifications and hotspot mutations such as L858R that promote proliferation have been detected in a significant fraction of non-small cell lung carcinomas and breast adenocarcinomas." (PMID 41681946, 2026). "The non-small cell lung cancer-associated epidermal growth factor receptor (EGFR) mutant L858R/T790M confers resistance to first- and second-generation tyrosine kinase inhibitors (TKIs)." (PMID 42212047, 2026). "Epidermal growth factor receptor (EGFR) gene mutations are the most common driver mutations in non-small cell lung cancer (NSCLC)." (PMID 42290055, 2026). "Leptomeningeal carcinomatosis (LMC) remains a devastating complication of epidermal growth factor receptor (EGFR)-mutated non-small cell lung cancer despite the availability of central nervous system (CNS)-active EGFR tyrosine kinase inhibitors (TKIs)." (PMID 42220682, 2026). "The emergence of epithelial growth factor receptor tyrosine kinase inhibitors (EGFR-TKIs) propelled EGFR-mutated patients of non-small cell lung cancer (NSCLC) into the era of precision medicine." (PMID 42100320, 2026). "Target therapy is effective for epidermal growth factor receptor (EGFR) mutation in non-small cell lung cancer (NSCLC)." (PMID 41438583, 2026). "This work presents the first thorough examination of epidermal growth factor receptor (EGFR) mutation prevalence in Kurdish patients with non-small cell lung cancer (NSCLC), identifying unique molecular and epidemiological traits." (PMID 42131887, 2026). "Mutated EGFR is the target of a therapy for non-small cell lung cancer (NSCLC) using tyrosine kinase inhibitors (TKIs) as treatment drugs." (PMID 41595675, 2026). "Tyrosine kinase inhibitors (TKIs) are common therapies for non-small cell lung cancers (NSCLC) harboring specific EGFR-activating mutations." (PMID 40722726, 2025). "The discovery of EGFR mutations has brought us novel targeted therapeutic approaches in advanced non-small-cell lung cancer." (PMID 39910007, 2025). "Osimertinib, a third generation EGFR inhibitor, is currently approved as first-line treatment for CNS metastatic disease in non-small cell lung cancer with EGFR mutations secondary to its high CNS penetrance and preclinical and clinical activity." (PMID 40094009, 2025). "Background and Objectives: Erlotinib, a tyrosine kinase inhibitor (TKI), is an established therapy for patients with metastatic non-small cell lung cancer (NSCLC) harboring epidermal growth factor receptor (EGFR) mutations." (PMID 41155830, 2025). "Predictive biomarkers assess the likelihood of a patient’s response to specific therapies, such as EGFR mutations in non-small cell lung cancer, to assist in targeted treatments." (PMID 39996991, 2025). "This mutation, common in non-small cell lung cancers (NSCLCs), led to the development of the first-generation EGFR-targeting TKI erlotinib (brand name: Tarceva)." (PMID 40649937, 2025). "Here, we explore the existing literature on disease patterns and management of central nervous system spread for EGFR-mutated non-small-cell lung cancer." (PMID 40805138, 2025). "Further classification analysis of these data showed that the mutations in EGFR exons in non-small cell lung cancer patients were mainly located in 19/28 (35.98%), 21/28 (32.40%), 20/28 (7.79%), 18/28 (7.01%), and mixed mutations between the four." (PMID 40732366, 2025). "EGFR mutation testing is the most common molecular test done for non-small cell lung cancer in our setting with a positive rate similar to that seen in the Asian population." (PMID 40112503, 2025).